INS (insulin)
Diseases named in the same sentence as INS in open-access papers (continued):
Sharing a sentence is not in itself a finding about the gene and the disease.
diabetes (continued). "UAE was higher in MWF-C and MWF-D compared to Wistar rats, with no impact of diabetes or insulin treatment observed." (PMID 38069331, 2023). "Hypoglycaemia remains a common side effect of the insulin treatment required by people with type 1 diabetes, and has not been eliminated through modern diabetes technologies." (PMID 36538062, 2023). "Obesity confers insulin resistance, often leading to type 2 diabetes mellitus (T2DM); chronic tissue inflammation has been observed in insulin target tissues—e.g., adipose, liver, muscle, pancreatic islets—and is thus understood to be a key component of the diabetes disease state." (PMID 37515062, 2023). "On the contrary, unlike some studies, our study found that diabetes mellitus in our diabetic patients was not necessarily dependent on insulin." (PMID 36577716, 2023). "A retrospective analysis of 156 ERCP investigations in patients with insulin-dependent and non-insulin-dependent diabetes mellitus Chronic pancreatitis and diabetes mellitus." (PMID 37101022, 2023). "In other cases, instead, not all the features selected turn out to be relevant for the accuracy of the predictor, demographic features, and insulin, for example, did not add any performance improvement for diabetes forecasting." (PMID 37047748, 2023). "Type 1 diabetes mellitus (T1DM), an autoimmune condition, occurs when the body’s immune system mistakenly attacks and destroys insulin-producing cells in the pancreas, leading to a critical deficit of insulin." (PMID 38203517, 2023). "This could, however, be due to the longer diabetes duration in HART-D trial participants, with 18.3% of the subjects on active insulin treatment (while insulin treatment was an exclusion criterion in DARE), or to the higher female population." (PMID 37836486, 2023). "Diabetes is a serious, chronic disease that occurs either when the pancreas does not produce enough insulin (a hormone that regulates blood glucose), or when the body cannot effectively use the insulin it produces." (PMID 36897872, 2023). "The interviewed patients, despite being people who have diabetes with complications, were not aware of the fundamental aspects of their own care and control, such as the use of insulin." (PMID 37377235, 2023). "Diabetes mellitus (DM) is a chronic disease where not enough insulin is produced by the pancreas or when one’s body cannot effectively make use of produced insulin." (PMID 37259043, 2023). "Studies revealed that there is an increase in the insulin sensitivity in mice which are having Fetuin-A knockout genes in them which shows the negative relation of the Fetuin-A with insulin sensitivity in diabetes." (PMID 36782201, 2023). "In relation to diabetes, NLE has been reported to have insulin secretagogue, PPARgamma antagonistic, and alpha-glucosidase inhibiting properties and may help improve glycemic control." (PMID 37305057, 2023). "In this type of diabetes, β-cells of the pancreas are dysfunctional and produce little to no quantity of insulin." (PMID 37662785, 2023). "Although these phenomena would suggest a diabetes protective effect of high iron, they do not factor in the deleterious effects of iron on insulin secretory capacity nor the fact that it is still possible to “eat one’s way through” this relative protection." (PMID 36137277, 2023). "In women without diabetes, a longitudinal study of a large cohort of 257 women showed that insulin and measures of insulin resistance changed over the menstrual cycle, with both reaching maximum levels during the luteal phase." (PMID 36833469, 2023). "A breakdown of concomitant dedication for diabetes showed that no participants were treated with insulin or insulin secretagogues in this subanalysis." (PMID 37514025, 2023). "Individuals with diabetes treated with BIL had increased plasma ALT activity compared to patients treated with conventional insulin, but the mechanism behind this effect is not clear." (PMID 36404376, 2023).
diabetes (continued). "Improve insulin sensitivity among hyperglycemic individuals with no prior diagnosis of diabetes mellitus." (PMID 37215217, 2023). "ROS is known to play a part in activation of intracellular stress kinases and inhibition of IRS-1, thus potentially influencing insulin signaling and to promote via GLUT-4 translocation and down streaming of AKT resulting in insulin resistance, obesity and diabetes mellitus." (PMID 37089941, 2023). "Diabetes is a chronic disease that occurs when the pancreas does not produce enough insulin (a hormone that regulates blood sugar) alternatively; when the body cannot effectively use the insulin it produces." (PMID 37179444, 2023). "PHPB intervention significantly improved diabetes-induced cognitive impairment without obvious differences in body weight gain and levels of plasma-glucose, cerebral-glucose and plasma-insulin." (PMID 37259448, 2023). "Diabetes mellitus (DM) occurs when the pancreas fails to secrete the necessary amount of insulin required to maintain a normal blood sugar level in the human body." (PMID 36904445, 2023). "In a real-world cohort of AF patients on edoxaban, diabetes requiring insulin therapy, rather than the presence of diabetes per se, appears to be an independent factor affecting the occurrence of thromboembolic events during follow-up." (PMID 35976428, 2023). "In diabetics, due to lack of insulin or impaired insulin actions because of insulin resistance, the elevated blood glucose fails to catabolize, and as a result, glucose converts to fatty acids in the liver." (PMID 37970436, 2023). "There are two principal types of diabetes: type 1 diabetes mellitus (DM1), which is due to the autoimmune destruction of beta pancreatic cells, and type 2 diabetes mellitus (DM2) that implies anomalies in secretion and insulin activity." (PMID 36979696, 2023). "For people without diabetes, it is guaranteed that the insulin level will increase with the glucose level; the insulin dynamic is predictable." (PMID 37631595, 2023). "Other studies on non-T1D populations, such as those with prediabetes or type 2 diabetes or those without diabetes, have shown that regular exercise and physical activity, especially when in line with the guidelines, can improve insulin sensitivity." (PMID 36833469, 2023). "Diabetes mellitus is primarily divided into two types, such as type 1 (insulin dependent) and type 2 (non-insulin dependent)." (PMID 37193696, 2023). "The population with type 1 diabetes mellitus (T1DM) would have to take insulin indefinitely because their bodies no longer make this hormone." (PMID 36751859, 2023). "Because insulin resistance in skeletal muscle is the major disruption of insulin action in type 2 diabetes, increasing muscle action of REG3A may contribute to the decrease of insulin resistance in diabetes and obesity." (PMID 36918710, 2023). "Although the most common cause is diabetes medication, including sulfonylureas and exogenous insulin, symptomatic hypoglycemia can occur in people who do not have diabetes mellitus." (PMID 36837857, 2023). "Many studies have shown that a single STZ dose damages pancreatic cells only partially, and diabetes occurs as a result of glucotoxicity (i.e., the state in which damaged β-cells are unable to produce insulin) rather than severe STZ toxicity." (PMID 36829539, 2023). "As it is well known that wound-healing defects are aberrant in diabetes, we investigated leukocyte influx into the air pouch of C57BL/6J- and KitW-Sh-STZ-induced diabetic mice infused with either saline, diluent, or insulin." (PMID 37626754, 2023). "Background/rationale: Diabetes is a chronic disease that occurs either when the pancreas does not produce enough insulin or when the body cannot effectively use its insulin, a hormone that regulates blood sugar." (PMID 37692985, 2023). "Metformin is frequently used to treat diabetes, because it does not increase the process of insulin secretion and cannot result in a blood glucose deficit." (PMID 37554894, 2023).
diabetes (continued). "Diabetes in patients in cluster D was well controlled, and there is no need to alter their insulin regime." (PMID 38875568, 2023). "In diabetes, the impairment of insulin secretion and insulin resistance contribute to hypertriglyceridemia, as the enzymatic activity of lipoprotein lipase (LPL) depends on insulin action." (PMID 37448184, 2023). "The patient did not have a history of diabetes or hypoglycemia, did not smoke or drink alcohol, did not take anti-diabetic drugs or insulin, and had grade II thyroid enlargement without eye protrusion." (PMID 37587407, 2023). "Type 2 diabetes mellitus is a condition in which the body’s cells do not respond well to the hormone insulin on the background of insulin resistance, and accounts for 90–95% of all diabetes mellitus in adults." (PMID 37213540, 2023). "The occurrence of major bleeding was similar in patients with diabetes not requiring insulin and in non-diabetic patients (1.10%/year vs 0.90%/year; HR 1.22, 95% CI 0.87–1.71, p = 0.24)." (PMID 35976428, 2023). "There are increasing attempts to improve the available algorithms for T2DM by including indices such as quantitative insulin sensitivity check index (QUICKI), homeostatic model assessment (HOMA), adiposity index (AI) and metabolic biomarkers to identify pre-diabetes and T2DM." (PMID 37505836, 2023). "Diabetes occurs when the body does not produce enough insulin (the hormone that regulates blood sugar) or the body cannot effectively use the insulin produced." (PMID 38974309, 2023). "Several clinical trials conducted in the 1980s demonstrated a detrimental effect of aspirin therapy on insulin sensitivity in people with and without diabetes." (PMID 36857596, 2023). "The development and transition of diabetes stages can be viewed as a continuum of increasing insulin resistance and decreasing insulin production if blood glucose levels are not optimal over time." (PMID 36607714, 2023). "The study included 69 insulin-treated diabetes patients and 36 non-insulin treated diabetes patients attending the diabetes clinic at the Mekelle Hospital in Ethiopia." (PMID 36778553, 2023). "Type-2-diabetes mellitus (T2DM) is a chronic metabolic disease defined by abnormally high blood glucose levels (hyperglycemia) due to impaired insulin secretion from pancreatic β-cells or insufficient cell response to insulin, resulting in insulin resistance." (PMID 38139843, 2023). "Acute COVID-19 children exhibited decreased adiponectin, and GIP and increased adipsin, leptin, C-peptide, insulin and ghrelin when compared with convalescent and control group of children without prior history of diabetes." (PMID 37013538, 2023). "For example, in an early study including 714 Mexican Americans without diabetes, both decreased insulin secretion and increased insulin resistance were shown to be independently associated with T2D development." (PMID 37432389, 2023). "Diabetes mellitus is a common metabolic disorder characterized by dysfunction of insulin secretion by pancreatic β cells, varying degrees of insulin resistance combined with relative lack of insulin." (PMID 36818396, 2023). "Hyperglycemia in the STZ-induced model of diabetes results from β cell dysfunctions since STZ destroys β cells located in the large islets in the pancreatic core, whereas the remaining β cells show insufficient and impaired insulin production." (PMID 36650229, 2023). "Specifically, many stand-alone diabetes digital apps do not integrate regulated medical devices, such as insulin pumps or continuous glucose monitors (CGMs)." (PMID 37440296, 2023). "Insulin desensitization was found in the brains of people who had PD, even if they did not have diabetes." (PMID 37791037, 2023). "A great majority of diabetics in the world suffer from type 2 diabetes mellitus, or non-insulin-dependent diabetes mellitus, a serious chronic disease that develops when the body does not produce enough insulin or is unable to use it effectively." (PMID 36902173, 2023).
diabetes (continued). "The typical treatment for CPI-triggered diabetes is insulin, but a detailed therapeutic method has not yet been established." (PMID 38106883, 2023). "Cross-sectional data for 1906 women without diabetes showed cyclic changes in glucose but not in insulin or measures of insulin resistance." (PMID 36833469, 2023). "Diabetes mellitus is the lack of insulin and can be divided into type 1 diabetes and type 2 diabetes." (PMID 37111730, 2023). "Carbachol, a muscarinic receptor 2 agonist which potentiates glucose-stimulated insulin secretion, could be of use in patients with WS1 diabetes." (PMID 36835101, 2023). "Among the current interventions not strictly limited for BMI, the DiRECT intervention (weight management based on primary care) in diabetes remission is significant, and SIIT (short-term intensive insulin therapy) also be recommended to be used in diabetes remission." (PMID 36810013, 2023). "Among those with diabetes, 483 (1.9%) were not on any treatment, 3236 (12.6%) had dietary control, 14 349 (55.8%) were on oral treatment and 7683 (29.9%) were insulin-dependent." (PMID 36924418, 2023). "In some studies, individuals classified as diabetics used drugs such as metformin and insulin, and they were not always categorized as controlled or uncontrolled T2D." (PMID 36986326, 2023). "A good glycemic response was seen following the addition of GLP-1 RA therapy with HbA1C reductions ranging from 0.40 to 0.94% regardless of baseline insulin dosage, baseline BMI, or duration of diabetes." (PMID 37589043, 2023). "Ketoacidosis is a metabolic complication that can arise in individuals with diabetes, especially when diabetes is uncontrolled, or there is a lack of sufficient insulin levels." (PMID 37818370, 2023). "Early screening of monogenic diabetes in children with AAB-negative diabetes can have a major impact on the choice of treatment, enabling oral glucose-lowering treatment instead of insulin injections, with benefits on glycaemic control and long-term complications." (PMID 36418577, 2023). "Furthermore, FOXM1-deficient mice exhibited reduced insulin secretion, whereas the activation of FOXM1 increased β-cell replication, enhanced insulin production, and improved glucose balance, rendering FOXM1 an appealing target for the management of diabetes." (PMID 37238726, 2023). "We have now shown that hepatic FASN deficiency ameliorated NAFLD and diabetes in Mc4r-KO mice by suppressing DNL, FAO, and gluconeogenesis and improving hepatic insulin signaling without inducing hypertriglyceridemia." (PMID 37681411, 2023). "Here, the authors show in a mice model that insulin action in the gut may play a protective role in the development of NASH and HCC in diabetes." (PMID 37852976, 2023). "Some families interested in pump therapy access pumps through Government means-tested subsidised Insulin Pump Program (IPP), administered by Juvenile Diabetes Research Foundation (JDRF); however, availability is limited in terms of both total number of pumps available and device type." (PMID 37361523, 2023). "Patients with preoperative long-duration diabetes had higher daily insulin requirements than those without diabetes or those with preoperative short-duration diabetes during both perioperative and long-term follow-up periods." (PMID 36860372, 2023). "Diabetes is a disease where no or insufficient insulin is available, or target organs cannot functionally respond to the insulin, which then places “metabolic pressure” on the pancreas." (PMID 37189396, 2023). "Type 1 diabetes mellitus (T1DM) or insulin-dependent diabetes mellitus is a metabolic disease characterized by the reduction or total absence of insulin production leading to high blood glucose concentrations." (PMID 37296126, 2023). "Diabetes mellitus is a chronic medical condition that is characterized by raised blood glucose levels as a result of very little or no insulin hormone production or insulin resistance in the body." (PMID 37138213, 2023).